DPP10 (dipeptidyl peptidase like 10)
Diseases named in the same sentence as DPP10 in open-access papers (continued):
Sharing a sentence is not in itself a finding about the gene and the disease.
ulcerative colitis (1 paper, 2022). An inflammatory bowel disease involving the mucosal surface of the large intestine and rectum. "AUC was higher than 0.8, indicating that these genes MST1L, OLFM4, and DPP10 are indicators of ulcerative colitis." (PMID 34939750, 2022). "Correlation between MST1L, OLFM4, and DPP10 in ulcerative colitis and immune infiltration cells." (PMID 34939750, 2022). "In addition, OLFM4 was only expressed in the ulcerative colitis samples and DPP10 was only found in the normal samples." (PMID 34939750, 2022). "However, the expression of DPP10 was strikingly decreased in the DSS‐induced ulcerative colitis group." (PMID 34939750, 2022). "Hence, these candidate biomarkers, MST1L, OLFM4, and DPP10, may be involved in the development of ulcerative colitis." (PMID 34939750, 2022). "To further validate the expression of these candidate biomarkers in ulcerative colitis, we determined mRNA levels of SGK1, CEP55, ACSL1, OLFM4, and DPP10 in LPS‐stimulated Raw264.7 cells by qPCR in in vitro bioassays." (PMID 34939750, 2022). "Of these candidate biomarkers, MST1L, OLFM4, and DPP10 were then validated in the GSE48958 dataset and were predicted to be strongly correlated with infiltrating immune cells of ulcerative colitis." (PMID 34939750, 2022). "To further validate these biomarkers' expression in ulcerative colitis, we determined mRNA levels of SGK1, CEP55, ACSL1, OLFM4, and DPP10 in lipopolysaccharides (LPS)‐stimulated Raw264.7 cells by quantitative reverse transcription‐polymerase chain reaction." (PMID 34939750, 2022). "Furthermore, to examine the model's accuracy in distinguishing between the healthy and ulcerative colitis groups, we further determine the area under the curve (AUC) of MST1L, OLFM4, and DPP10 in GSE48958 and the combined data from GSE36807 and GSE65114." (PMID 34939750, 2022).
tumor (6 papers, 2010 to 2025). "One large deletion within the Dipeptidyl-Peptidase 10 (DPP10) gene resulted in altered truncated fusion transcript in the tumor." (PMID 36362209, 2022). "In fact, in some samples the expression of three of these genes, encoding the non-protease homologue DPP10, the proprotein convertase PCSK2 and the mannan-binding lectin serine peptidase 3 MASP3, are reduced up to a thousand fold in tumor tissue when compared to normal mucosa." (PMID 24243807, 2013). "One of the rearrangements resulted in a large deletion within the dipeptidyl-peptidase 10 (DPP10) gene (exons 4–25) and produced the expected truncated fusion transcript uniquely in the transcriptome of the tumor, but not of the normal lung." (PMID 20485525, 2010).
cancer (4 papers, 2010 to 2026). A tumor composed of atypical neoplastic, often pleomorphic cells that invade other tissues. "In addition, DPP10 is part of the “DPP-IV activity and/or structure homologues” (DASH) molecules, which have deregulated expression in multiple human cancers determining their pathobiological relevance in carcinogenesis." (PMID 20485525, 2010).
respiratory disease (2 papers, 2018 to 2026). "In addition, recent studies have shown that DPP10 genetic variants affect lung function decline in ageing, and have also been associated with aspirin-exacerbated respiratory disease." (PMID 29361513, 2018).
DPP10 also shares sentences with these, for which no sentence is quoted: glioma (3 papers); psychiatric disorder (3); colorectal cancer (2); neurodegenerative disease (2); neurodevelopmental disorder (2); acute respiratory distress syndrome (1); adenocarcinoma (1); alcohol dependence (1); Allergy (1); bipolar disorder (1); childhood asthma (1); colon cancer (1); Creutzfeldt Jakob disease (1); eye problems (1); frontotemporal lobe dementia (1); glaucoma (1); infection (1); Intellectual disability (1); lung (1); lung adenocarcinoma (1); lung carcinoma (1); nasopharyngeal carcinoma (1); neurofibromatosis type 1 (1); neurological disease (1); non-small cell lung carcinoma (1); Obesity (1); pancreas cancer (1); psoriasis (1); pulmonary fibrosis (1); pulmonary hypertension (1).
A further 2 diseases each share a sentence with DPP10 in 1 paper.